BAX (BCL2 associated X, apoptosis regulator)
Diseases named in the same sentence as BAX in open-access papers (continued):
Sharing a sentence is not in itself a finding about the gene and the disease.
breast cancer (continued). "Artichoke polyphenols modify Bcl-2 and BAX expression in human breast cancer cell line MDA-MB-231, leading to a pro-apoptotic situation, which was accompanied with the upregulation of p21." (PMID 29112149, 2017). "On treatment with green tea polyphenols and EGCG, a significant reduction in cell growth associated with apoptotic changes, such as stimulation of BAX, cleavage of PARP, and down-regulation of Bcl-2, was observed in MD-MB-231 human breast cancer cells." (PMID 27657126, 2016). "The ratio of the anti-apoptotic gene/pro-apoptotic gene was measured by semi-quantitative RT-PCR, and all 5-FU treated cells showed low Bcl-2/BAX ratios due to induction of apoptosis in breast cancer cells." (PMID 26716512, 2016). "In this study, a decreased level of Bcl-2 and increased level of BAX were observed in breast cancer cells after ZLD1039 treatment." (PMID 26868841, 2016). "In this investigation, 5-FU and IFN-β stimulated BAX overexpression for apoptosis in breast cancer cells via synergistic effects." (PMID 26716512, 2016). "Decreased BAX expression has been reported in breast cancer, hepatocellular carcinomas and chemoresistant B-cell chronic lymphocytic leukemia (CLL)." (PMID 27386062, 2016). "It has been reported that 17β-estradiol inhibits MDA-MB-231 breast cancer cell growth by increasing BAX/BCL-2 and reducing pERK1/2, while it is mostly agreed that it promotes proliferation and cell-cycle progression of MCF-7 cells." (PMID 27101408, 2016). "We first examined the BAX gene on vinorelbine, an anti-mitotic chemotherapy drug that is approved for breast cancer and non-small cell lung cancer treatment by the U.S. Food and Drug Administration (FDA)." (PMID 25360158, 2014). "In contrast, bax−/− MEFs or down-regulation of BAX in breast cancer cells showed similar paclitaxel sensitivity as wild-type MEF or control cells, respectively." (PMID 23577147, 2013). "Similarly, 13-O-acetylsolstitialin A, derived from Centaurea cyanus activated the decrease of MMP and increased BAX/Bcl-2 ratio to induce apoptosis in breast cancer." (PMID 38966207, 2024). "We next measured the expression of apoptosis-associated proteins BAX, Bcl-2 and PUMA in mammary tumor tissue from each group in order to determine the impact of single and combined BSp and/or Ash administration on apoptosis induction in mammary tumor." (PMID 38802425, 2024). "Moreover, PGG was found to downregulate the expression of HURP and BCL-2, and increase the expression of BAX to induce apoptosis as an anti-ER breast cancer." (PMID 37050924, 2023). "For example, it has been proven that quercetin suppressed the activation of PI3K and AKT, which increased the ratio of BAX/Bcl-2 to induce apoptosis of breast cancer cells, as well as significantly inhibiting the growth and metastasis of CD44+/CD24 breast cancer stem cells in vivo." (PMID 36900408, 2023).
breast cancer (continued). "Furthermore, RRS1 also induces apoptosis resistance in breast cancer cells through the ERK/Bcl-2/BAX signaling pathway." (PMID 37049702, 2023). "Sehrawat suggested that BAX activation can mediate the selective death of human breast cancer cells and might provide some direction for breast cancer treatment." (PMID 35269511, 2022). "Slc25a24, Cnpy2 and BAX overexpression was reported in breast cancer." (PMID 36151122, 2022). "We demonstrated that deletion or pharmacological inhibition of MCL-1 with either S63845 or A1210477 BH3-mimetics impaired the tumorsphere-forming capacity of breast cancer cells, and that genetic ablation of pro-apoptotic effector proteins BAX and BAK abrogates this effect." (PMID 35349392, 2022). "The role of BAX apoptosis signaling in breast cancer has been widely studied." (PMID 35269511, 2022). "Furthermore, several drugs can activate BAX to participate in the pyroptosis of breast cancer and exert its anticancer effects." (PMID 36119049, 2022). "A reduced level of BAX expression is an adverse prognostic factor in breast cancer." (PMID 34746770, 2021). "Dysregulation of apoptosis due to imbalances in BAX/BCL-2 levels may result in breast cancer pathogenesis." (PMID 33708254, 2021). "Through gain and loss of function and rescue experiments, we confirm that MIR200CHG regulates the expression of tumor-associated proteins CDKN2A, cyclin D1, cyclin E1, BCL2, BAX, MMP1, MMP2, and MRP1 by binding YB-1, thereby promoting breast cancer proliferation, invasion, and resistance." (PMID 34272387, 2021). "Therefore, the aim of the present case-control study was to investigate the association of BCL-2 (-938C>A), BAX (-248G>A), and HER2 Ile655Val polymorphisms with breast carcinoma risk in Indian population." (PMID 33708254, 2021). "FAM83H-AS1 deregulation is associated with migration and cell death impairment in BRCA samples and breast cancer cells, and may regulate a plethora of cancer-related gene targets, such as p63, BAX, LEP and CLDN1." (PMID 32839509, 2020). "It has been reported that melatonin could downregulate the expression of MYC and upregulate the expression of BAX to stimulate the apoptotic effects in breast cancer cells." (PMID 32689938, 2020). "Moreover, our results for the first time demonstrated that Nar markedly enhanced the expressions of BAX, a major pro-apoptotic mediator, and furthermore, reduced the expression of Bcl-2 as the main anti-apoptotic factor in breast cancer cells." (PMID 33680016, 2020). "Specifically, we found that in MCF7 breast cancer cells, iodoacetate mediates apoptosis by upregulating BAX/BAK gene expression which in turn induced caspase 9 and p21 activation leading to increased cytotoxicity as confirmed by flow cytometry multiple measures." (PMID 31551501, 2019). "HIF-1α dependent BAX expression during hypoxia revealed that after certain extent of hypoxia induction, over expression of BAX conquers the effect of anti-apoptotic proteins and ultimately leads to apoptosis in breast cancer cells." (PMID 30876462, 2019). "Apoptosis plays important roles in the potential of quercetin to inhibit the proliferation of human MDA-MB-453 breast cancer cells that are mediated by up-regulation of BAX and down-regulation of Bcl-2 expression, as well as cleavage of caspase-3 and PARP proteins." (PMID 27657126, 2016). "However, folic acid supplementation appeared to promote apoptosis in the sentinel mammary tumors as evidenced by increased expression of the pro-apoptotic protein BAX as well as PARP." (PMID 24465421, 2014).
breast cancer (continued). "Meanwhile, in breast cancer, the degradation of BAX could contribute to its malignancy." (PMID 39074253, 2024). "They investigated 4ICD expression in ER+ breast cancer cell lines and speculated that tamoxifen promoted mitochondrial accumulation of 4ICD and activated apoptotic proteins such as Bcl-2 homologous antagonist/killer(BAK) and Bcl-2 associated X protein(BAX)." (PMID 25003574, 2014). "Elevated BAX expression and PARP-1 cleavage in MCF-7 and MDA-MB-231 breast cancer cells treated with nanoencapsulated PTX indicate that apoptosis is the primary mechanism of cell death, regardless of the nanocarrier type." (PMID 41790974, 2026). "Next, we checked expression levels of the effectors BOK, BAX, and anti-apoptotic BCL-2 family members in LUAD, LUSC, and breast cancer (BRCA)." (PMID 39996719, 2025). "The BAX gene was recurrently found in colorectal cancer, renal cancer, and ovarian cancer, and the PIK3CA gene belonged to renal cancer and breast cancer." (PMID 38463169, 2024). "The BAX/BCL2 ratio in MCF-7 cells was 1.2 after 24 h of cultivation with CIMVs-TRAIL, which also confirms the induction of apoptosis in breast cancer cells." (PMID 36661524, 2023). "To determine the underlying molecular mechanism of cell death, we analyzed how treatment of breast cancer cell lines affected the expression of genes involved in apoptosis, such as BCL-2, BAX, Cas-3, Cas-8, and Cas-9." (PMID 36770598, 2023). "Apoptosis resulted in all the treated breast cancer cell lines, as evidenced by significant decreases in BCL-2 levels and increases in BAX levels." (PMID 36770598, 2023). "Previous reports have shown that miRNA-128-3p suppresses BAX expression by targeting the 3′UTR of BAX mRNA, and the miR-128-3p/BAX axis is involved in the regulation of the chemosensitivity of breast cancer cells." (PMID 36672566, 2022). "Another study presented the enrichment of BAX, CASPASE-3, CASPASE-8, and CASPASE-9 with juglone to inhibit the growth of breast cancer cells." (PMID 33680036, 2020). "It has been shown that MED23 knock‐down promotes tumorigenicity and inhibits apoptosis through a decrease of BAX expression, yet conversely, MED24 knock‐down in breast carcinoma cells lead to diminished cell proliferation and DNA synthesis." (PMID 38831555, 2020).
breast cancer (continued). "Enrichment analysis and experimental validation demonstrated that ADQ might improve breast cancer chemosensitivity via inhibiting caveolin-1, which further triggered expression changes of cell cycle-related proteins p21/cyclinB1 and apoptosis-associated proteins PARP1, BAX and Bcl-2." (PMID 30333750, 2018). "Combinatorial treatment-induced BAX and PUMA upregulation; therefore, mechanistically decreased cellular resistance to apoptotic stimuli by lowering the apoptotic threshold and consequential increase apoptotic cell death in mammary tumor." (PMID 38802425, 2024). "However, we found underexpression of EEF2 and GLRX2 proteins involved in ROS; MTX2 in MMO; USP30 in MIT; TSPO in MIT and PPM processes; BAX in FUS; and MTFR1L and MIEF1 in FIS compared to luminal A and basal-like breast cancer tumors." (PMID 35327574, 2022). "MTT assay, gene expression analysis (BAX, BCL-2, and β-catenin), apoptosis analysis, TEM, cell cycle assay, ELISA, and cell migration assays were conducted to perform the cell death analysis of lung cancer and breast cancer, compared to the marketed product." (PMID 36457709, 2022). "Finally, a recent study suggested that the tricistronic expression of MOAP1, BAX, and RASSF1A enhances chemo-sensitization in breast cancer cell lines." (PMID 35269511, 2022). "BAX and BCL2 are known prognostic biomarkers for breast cancer." (PMID 35269511, 2022). "The expression of key markers associated with proliferation (MKI67, PCNA, CCNB1, MYBL2, BUB1, CCND1), apoptosis (BCL2, CASP7, CASP8, CASP9, CASP3, BAX, APAF1), differentiation (CDH1, CD24, EPCAM, ESR1, NGFR, RUNX1), and breast cancer stemness (CD44, ITGA6, DNER, ALDH1A3, ABCG2, PROCR) was assessed." (PMID 35183258, 2022). "In summary, our study demonstrates that DUSP16 targets JNK and p38 to regulate the common cell death pathway, the BAX/caspase 3–caspase 9 pathway, in various types of solid tumors, including NPC, CRC, gastric cancer, and breast cancer to regulate chemotherapy-induced apoptosis." (PMID 33863904, 2021). "The knockdown of RPS15A by shRNA in breast cancer cell line ZR-75-30 and BT474 mediates apoptosis via the activation of caspase-3 and PARP cleavage, the up-regulation of Bad and BAX and the down-regulation of Bcl-2 confirming the importance of RPS15 in the modulation of breast cancer development." (PMID 34873618, 2021).
breast cancer (continued). "However, they also often overexpress pro-apoptotic proteins BAX or BAK: for example, BAX was reported to be overexpressed (alone or in combination with BCL-2) in about one third of breast cancers or in several pancreatic cancer cell lines." (PMID 33920941, 2021). "The ability of MCL-1 inhibitor S63845 to restrict human breast cancer stem cell growth was also negated in the absence of BAX/BAK, clearly illustrating the importance of canonical anti-apoptotic MCL-1 function in breast cancer stem cells." (PMID 33785871, 2021). "It has been hypothesized that CTCF could enhance tumorigenesis through the inhibition of pro-apoptotic protein BAX, which was increased after CTCF knockdown in breast cancer cell lines." (PMID 34065345, 2021). "In addition to other members, decreased BAX/BCL-2 ratio and elevated MCL-1 expression were reported to be closely related with PTX resistance in breast cancer." (PMID 32547883, 2020). "Similarly, apoptotic modulation of MCF7 breast cancer cells was attributed to Crocus sativus extract (CSE) and its major constituent crocin through time-dependent decrease of Bcl-2, upregulation of BAX, dowregulation of caspase-8 and -9 and cleaved caspase-3." (PMID 32859058, 2020). "S63845-induced apoptosis has previously been shown to be BAK- but not BAX-dependent in breast cancer cells." (PMID 31801941, 2019). "Importantly, we show that this is through induction of apoptosis in a BAX/BAK and caspase-dependent manner validating the on-target effect of these drugs on mitochondrial-dependent apoptosis on breast cancer cells." (PMID 29339815, 2018). "We assessed the pro-apoptotic gene BAX and the anti-apoptotic gene BCL-2 with combinatorial WA and SFN as well as singly administered SAHA and found there to be an inverse relationship in these treated breast cancer cells." (PMID 28534825, 2017). "Although the Bcl-2/BAX ratio for induction of apoptosis showed the greatest decrease in response to 0.5 μg/ml of 5-FU, we selected the concentration of 1.0 μg/ml 5-FU following western blot analysis for co-treatment with human IFN-β in breast cancer cells." (PMID 26716512, 2016). "Moreover, using a genome-wide CRISPR knockout screen, we found that deletion of BAK, but not BAX, led to resistance to S63845 in the SK-RB-3 breast cancer cell line." (PMID 40075071, 2025). "Additionally, in breast cancer cells MCF-7 and MDA-MB-231, Bcl-2 decreased and BAX increased." (PMID 36142874, 2022). "Importantly, MCL-1 was required for breast cancer stem cell function in vitro and this was also due to MCL-1’s canonical anti-apoptotic function since it could be ablated by deletion of BAX/BAK and targeted with MCL-1-specific BH3-mimetic drugs." (PMID 33785871, 2021). "However, few studies could perfectly explain the role of BAX and ATG16L2 in breast cancer treatment resistance." (PMID 33796128, 2021). "To substantiate the finding on BAX in DUSP16-mediated cisplatin resistance, we treated various types of vector- and DUSP16-overexpressing cancer cells including NPC HK-1, CRC DLD-1, gastric cancer NUGC3, and breast cancer MDA-MB-231 cells with BAX inhibitor Peptide V5." (PMID 33863904, 2021). "In vitro studies showed that MDA-7/IL-24 induced G2/M cell cycle arrest in breast cancer cells via downregulation of AKT-GSK3β and upregulation of cyclin-dependent kinase inhibitor and apoptosis by activation of caspase-dependent signaling pathways and BAX signaling." (PMID 26474456, 2015).